MSL3 (MSL complex subunit 3)
Description:
Non-catalytic component of the MSL histone acetyltransferase complex, a multiprotein complex that mediates the majority of histone H4 acetylation at 'Lys-16' (H4K16ac), an epigenetic mark that prevents chromatin compaction. The MSL complex is required for chromosome stability and genome integrity by maintaining homeostatic levels of H4K16ac. The MSL complex is also involved in gene dosage by promoting up-regulation of genes expressed by the X chromosome (By similarity). X up-regulation is required to compensate for autosomal biallelic expression (By similarity). The MSL complex also participates in gene dosage compensation by promoting expression of Tsix non-coding RNA (By similarity). Acts as a histone reader that specifically recognizes and binds histone H4 monomethylated at 'Lys-20' (H4K20Me1) in a DNA-dependent manner and is proposed to be involved in chromosomal targeting of the MSL complex. May play a role X inactivation in females.
Synonyms: MSL3L1; MRSXBA; MRXS36; MRXSBA
Tractability: Small molecule: a structure with a bound ligand is known. PROTAC: ubiquitination databases record sites on it; its protein half-life has been measured.
Gene: Protein-coding gene on chromosome X (11,758,159 to 11,775,772, forward strand). Ensembl gene ENSG00000005302.
Subcellular location: Nucleus
Subcellular location (Human Protein Atlas): Nucleoplasm
Pathways (Reactome):
Chromatin organization: HATs acetylate histones
Gene Ontology:
Molecular function: DNA binding; histone H4K16ac reader activity; histone reader activity; protein binding
Biological process: positive regulation of DNA-templated transcription; regulation of DNA-templated transcription; regulation of transcription by RNA polymerase II; chromatin organization
Cellular component: MSL complex; nucleus; nucleoplasm
Gene-disease validity (ClinGen):
ClinGen rates the evidence that MSL3 causes each of these diseases.
Basilicata-Akhtar syndrome (X-linked): Definitive.
Homologues: Orthologues: chimpanzee MSL3 (100% identical), macaque MSL3 (99% identical), pig MSL3 (96% identical), guinea pig MSL3 (96% identical), rat Msl3 (89% identical), mouse Msl3 (88% identical), dog MSL3 (88% identical), tropical clawed frog msl3 (55% identical), Drosophila melanogaster msl-3 (26% identical), Caenorhabditis elegans mrg-1 (16% identical), Caenorhabditis elegans cec-7 (13% identical). Paralogues in human: MSL3B (60% identical), MORF4L1 (22% identical), MORF4L2 (16% identical).
Diseases named in the same sentence as MSL3 in open-access papers:
MSL3 is named in the same sentence as 13 diseases in open-access papers, as found by Europe PMC text mining. Sharing a sentence is not in itself a finding about the gene and the disease. The quoted sentences say what the papers report.
Basilicata-Akhtar syndrome (3 papers, 2024). "Basilicata-Akhtar syndrome is an ultrarare cause of syndromic development delay, resulting from the loss of the MSL3 gene, which results in pronounced loss of H4K16ac." (PMID 39286690, 2024). "A heterozygous or hemizygous pathogenic variation in male-specific lethal 3 (MSL3) causes the uncommon X-linked condition known as Basilicata-Akhtar syndrome, which is characterized by a global developmental delay that is evident from infancy, feeding difficulties, and muscle hypotonia." (PMID 39286690, 2024). "Pathogenic mutations of MSL3 have been reported in two cohorts with Basilicata-Akhtar syndrome." (PMID 38702431, 2024). "The sample was sent for reanalysis, which revealed a hemizygous single base pair deletion in exon 8 of the MSL3 gene on chromosome X (p.Ser297ValfsTer19; ENST00000312196.10), which was a likely pathogenic variant known to cause Basilicata-Akhtar syndrome." (PMID 39286690, 2024). "Importantly, re-classification of MSL3 as an inactive gene precludes escape from inactivation as an explanation for the equal penetrance of Basilicata-Akhtar syndrome in affected males and females." (PMID 39632794, 2024).
developmental delay (2 papers, 2021 to 2024). "The early Anopheles phenotype is also very different from the consequences of MSL3 loss in humans, which is associated with global developmental delay post birth affecting both male and female individuals." (PMID 34266874, 2021).
cervical cancer (1 paper, 2023). A primary or metastatic malignant neoplasm involving the cervix. "In particular, seven genes showed higher expression in cervical cancer and positively correlated with EMT scores, including CSRP2BP, LPCAT1, NAT14, CREBBP, MSL3, ATF2 and GNPNAT1." (PMID 37845756, 2023).
idiopathic interstitial pneumonia (1 paper, 2021). A class of diffuse lung diseases that typically affect the pulmonary interstitium, although some also have a component affecting the airways (for instance, Cryptogenic organizing pneumonitis). "In addition, the expression of Msl3 gene was higher by 85.2 fold in patients with idiopathic interstitial pneumonia (IIP) when compared with the control." (PMID 34367133, 2021).
ovarian carcinoma (1 paper, 2019). A malignant neoplasm originating from the surface ovarian epithelium. "In ovarian cancer cases, low expression of MSL3, ZNF691 and VPS45 was related to poor prognosis." (PMID 31578411, 2019). "Using another ovarian cancer clinical dataset, (GSE3149), the survival for patients with tumors having low expression of MSL3 and ITGB3BP was again significantly shorter than that of the high expression group (p < 0.05 for each)." (PMID 31578411, 2019). "In summary, using a functional genomics screen, we identified six novel genes, MSL3, ZNF691, VPS45, ITGB3BP, TLE2, and ZNF498, that regulate the proportion of SP cells in ovarian cancer." (PMID 31578411, 2019). "In this study, we identified six novel genes, MSL3, ZNF691, VPS45, ITGB3BP, TLE2, and ZNF498 whose expression altered the proportion of the SP cells of ovarian cancer cells through a functional genomics screen." (PMID 31578411, 2019). "In conclusion, through a functional genomics screen using an shRNA library we identified six novel genes; MSL3, ZNF691, VPS45, ITGB3BP, TLE2 and ZNF498, whose downregulation individually increased the proportion of SP cells and the malignant phenotypes of ovarian cancer." (PMID 31578411, 2019).
tumor (2 papers, 2024 to 2025). "Significant correlations were observed, with Spearman coefficients ranging from 0.031 to 0.526 (all p < 0.05), supporting the notion that MSL1 and MSL3 cooperatively regulate CD274 expression and contribute to tumor immune escape." (PMID 41409271, 2025).
cancer (1 paper, 2025). A tumor composed of atypical neoplastic, often pleomorphic cells that invade other tissues. "To test this possibility in a broader oncogenic context, we analyzed the correlation between MSL1, MSL3, and CD274 expression across multiple cancer types using the TIMER2.0 database." (PMID 41409271, 2025).
MSL3 also shares sentences with these, for which no sentence is quoted: Autoimmunity (1 paper); breast carcinoma (1); genetic disorders (1); neurodegenerative disease (1); neurodevelopmental disorder (1); prostate carcinoma (1).